LGALS1 (galectin 1)
Diseases named in the same sentence as LGALS1 in open-access papers (continued):
Sharing a sentence is not in itself a finding about the gene and the disease.
lymph node metastasis (10 papers, 2014 to 2025). "In agreement with findings of the other study, we found that staining intensity of Galectin-1 in stromal cells were significant associated with short patient survival, tumor stage and lymph node metastasis." (PMID 24595374, 2014). "The stromal galectin-1 expression were significantly higher in patients with lymph node metastasis (p = 0.041)." (PMID 26589590, 2015). "Patients with lymph node metastasis had higher serum galectin-1 levels (P = 0.002)." (PMID 26448934, 2015). "Finally, a retrospective study revealed that galectin-1 levels in blood circulation negatively correlates with overall survival and positively correlates with lymph node metastasis of the patients." (PMID 25605013, 2015). "In this study, we found that galectin-1 could be a marker for prediction of lymph node metastasis." (PMID 26448934, 2015). "Galectin-1 but not galectin-3 was associated with lymph node metastasis." (PMID 26448934, 2015). "During the progression of CRC, galectin-1 is often significantly changed, meaning that overexpression of galectin-1 correlates with poorly differentiated, invasive form of CRC with lymph node metastasis and shorter patient survival." (PMID 35611243, 2022). "Multivariate analysis of disease-specific survival was performed for tumor galectin-1 intensity by correcting for FIGO stage, lymph node metastasis and vaso-invasion." (PMID 26066796, 2015). "Tumor size and the presence of vaso-invasion or lymph node metastasis were not significantly different between samples with or without expression of galectin-1, -3 or -9 either in the tumor epithelium or stroma." (PMID 26066796, 2015). "However, all cases of papillary carcinoma associated with lymph node metastasis were positively stained with galectin-1, while 54.8% (17/31) of negative lymph node metastasis cases were positive for the marker, and 45.2% (14/31) of cases with no lymph node metastasis were negative for galectin-1." (PMID 41480246, 2025).
non-small cell lung carcinoma (10 papers, 2014 to 2024). A group of at least three distinct histological types of lung cancer, including non-small cell squamous cell carcinoma, adenocarcinoma, and large cell carcinoma. "Recently, the carcinogenesis of LGALS1 has been gradually revealed, such as in non-small cell lung cancer cells, head and neck cancer." (PMID 38965225, 2024). "Existing literature suggests that NCAPG promotes oncogenesis in non-small cell lung cancer cells by upregulating LGALS1 expression." (PMID 37335105, 2023). "Several studies had proposed the role of tumor galectin-1 in the clinical outcomes of non-small cell lung cancer." (PMID 35280768, 2022). "Up-regulation of LGALS1 expression can not only promote the occurrence and development of non-small cell lung cancer cells, but also promote the proliferation and cell cycle progression of esophageal squamous cell carcinoma cells." (PMID 36712844, 2022).
thyroid cancer (10 papers, 2010 to 2025). "Our results support that galectin-1 is an important diagnostic marker for thyroid carcinoma, given its involvement in cell migration, proliferation, tumor growth, and invasion." (PMID 41480246, 2025). "As supported by our results, galectin-1 expression in tissue specimens from thyroid cancer patients could be a reliable diagnostic marker for thyroid carcinomas." (PMID 38139416, 2023). "For molecular cancer imaging, USPIOs functionalized with galectin-1-targeting peptides (P7) were explored for thyroid cancer imaging, leveraging galectin-1’s role in tumor progression and immune suppression." (PMID 40286158, 2025). "In the present Special Issue of the International Journal of Molecular Sciences focused on galectins in cancer and translational medicine, other experiences with galectin-1, galectin-3 and thyroid cancer are reported by different research groups." (PMID 29393868, 2018). "Additionally, USPIO nanoparticles functionalized with galectin-1 peptides have demonstrated 100% specificity in thyroid cancer imaging, helping to reduce unnecessary surgical procedures." (PMID 40286158, 2025). "Proteomic profiling has also suggested galectin-1 as a potential thyroid cancer biomarker." (PMID 37547301, 2023). "For example, the Galectin-1 inhibitor showed significant anti-cancer effects both in vitro and in vivo in thyroid cancer lines expressing Gal-1, and the Galectin-1 inhibitor had been used to treat B-cell precursor acute lymphoblastic leukemia and head and neck squamous cell carcinomas." (PMID 36712844, 2022). "This study investigates the importance of the two immunohistochemical markers (galectin-1 and TROP-2) in differentiating benign and malignant thyroid lesions and between follicular and thyroid carcinoma." (PMID 41480246, 2025). "We previously identified by phage display two peptides (P1 and P7) targeting galectin-1, with the goal of developing imaging probes for non-invasive diagnosis of thyroid cancer." (PMID 32183292, 2020).
bladder cancer (9 papers, 2013 to 2025). "The altered expression of galectins has been implicated in bladder cancer malignancy, and both galectin-1, -2, -3, and -8 were suggested as potential disease markers and possible targets for bladder cancer therapy." (PMID 29207682, 2017). "Using a multiplexed immunosensor, galectin-1 was found to be increased in invasive bladder cancer cell lysates, suggesting its potential as a biomarker for distinguishing different bladder cancer grades." (PMID 40252176, 2025). "We further examined LGALS1 expression in bladder cancers of different levels of invasiveness from the GSE32894 data set; LGALS1 mRNA levels increased significantly in muscle invasion bladder tumors (p < 0.001)." (PMID 32225123, 2020). "Methods capable of detecting whole bladder cancer cells shed in urine are typically based on cell size, cellular features or the expression of specific proteins (e.g., intracellular galectin-1 or EpCAM)." (PMID 32521780, 2020). "This study ultimately suggests that galectin-1 constitutes a valid bladder cancer cell biomarker capable of being used in effective targeted therapies." (PMID 29207682, 2017). "More recently, a multiplexed immunosensor has been developed for the detection of specific biomarkers galectin-1 and lactate dehydrogenase B present in different grades of bladder cancer cell lysates." (PMID 29207682, 2017). "Recently, a photodynamic therapeutic approach targeting galectin-1 in bladder cancer cells and xenografts has inhibited tumour growth and enabled selective cytotoxicity in cancer cells, preventing undesired phototoxicity in the surrounding healthy tissues." (PMID 29207682, 2017). "Using confocal fluorescence microscopy, we observed co-localization of PcGal16 with galectin-1 inside bladder cancer cells." (PMID 24763311, 2014). "Previous reports demonstrate that annexin V and transthyretin were downregulated and galectin-1 was increased in bladder cancer." (PMID 23374291, 2013). "Interestingly, in contrast to galectin-3 and galectin-1, galectin-8 appears to play an opposing role in bladder cancer progression." (PMID 40252176, 2025). "Highly consistent with our single-cell data analysis, a previous study reported that bladder cancer cells with LGALS1 silencing and GAS6 depletion could reduce cell proliferation, lower invasive capability, and lower clonogenicity (PMID: 27440446 and PMID: 32547108)." (PMID 37745978, 2023). "Knockdown of galectin-1 and GLUT1, via small interfering RNA (siRNA), in bladder cancer cells decreases intracellular uptake and phototoxicity of PcGal16." (PMID 24763311, 2014). "Although the PcGal16 uptake was quite similar in the two bladder cancer cell lines, the expression of carbohydrate-binding proteins GLUT1 and galectin-1 is different amongst them." (PMID 24763311, 2014). "Although a similar PcGal16 uptake was observed in the two bladder cancer cell lines, both GLUT1 and galectin-1 may contribute for its specificity modulating the intracellular uptake." (PMID 24763311, 2014). "Furthermore, high levels of LGALS1 mRNA were expressed at the advanced stage of bladder cancer (stages 3 and 4) and not at the early stage (stages 1 and 2) in the TCGA cohort." (PMID 32225123, 2020).
head and neck cancer (9 papers, 2017 to 2025). A primary or metastatic malignant neoplasm affecting the head and neck. "Although our study showed that LGALS1 was associated with FAM in early metastasis of head and neck cancer, its exact molecular mechanism remained unclear." (PMID 40881692, 2025). "Upon demonstrating uptake of TDEs by T cells, we further show that these dysfunction-causing exosomes are secreted by a number of different head and neck cancer cell lines, and contain unique proteins, including galectin-1(Gal-1), which is known to play a role in immune regulation." (PMID 28806909, 2017). "In head and neck cancers, galectin-1 expression correlates with poor response to immune checkpoint inhibitors and in murine models, galectin-1 over-expressing cell lines prevented T-cell migration into the cancer." (PMID 33187209, 2020). "In addition, LGALS1 may serve as a novel target for fatty acid metabolism for the treatment and prognosis of head and neck cancer." (PMID 40881692, 2025). "Galectin-1 may drive T-cell exclusion and promote immunotherapy resistance in head and neck cancer." (PMID 37433225, 2023). "Data from head and neck cancer demonstrated that galectin-1 inhibition enhances anti-PD1 therapy, suggesting that a combination of galectin-1 inhibitors and anti-PD1/PDL1 immune checkpoint synergize for cancer treatment." (PMID 34572756, 2021). "In head and neck cancer, TAEs have been shown to induce a suppressor phenotype in CD8+ T cells in the synergistic action of exosomal proteins such as galectin-1 (Gal-1) and RNA." (PMID 33183286, 2020). "Galectin-1 (GAL1) reprograms the TECs to upregulate PD-L1 and death signal GAL9 and therefore drives T cell exclusion from the TME and is shown to exacerbate immunotherapy resistance in head and neck cancer." (PMID 38726320, 2024).
Hodgkins lymphoma (9 papers, 2011 to 2023). A heterogeneous group of malignant lymphoid neoplasms of B-cell origin characterized histologically by the presence of Hodgkin and Reed-Sternberg (HRS) cells in the vast majority of cases. "It was reported that there were abundant Th2 cells in classical Hodgkin lymphomas, which was proved to be the result of galectin-1 stimulation." (PMID 37047471, 2023). "In the group of patients presenting a nodular sclerosis subtype, the immune profile switched at relapse, with an upregulation of LGALS1 and TGFB1 and downregulation of CD163, CD274, HGF, IL15, and ICOS." (PMID 36230815, 2022). "Galectin-1 can serve as a predictive biomarker for relapsed or refractory Hodgkin lymphoma, and its serum levels reflect tumor burden and adverse clinical features." (PMID 30237983, 2018). "Overexpression of galectin-1 is correlated with activation of AP-1 pathway in malignant cells of Hodgkin lymphoma." (PMID 30237983, 2018). "In Hodgkin lymphomas, galectin-1 reduces anti-tumor T cell activity, promoting the expansion of CD4+CD25+Foxp3+ Tregs." (PMID 29258207, 2017). "In hematological malignancies, increased galectin-1 serum levels are correlated with increased tumor burden in Hodgkin lymphoma patients and this lectin is highly expressed in cutaneous T-cell lymphomas cells and chronic lymphocytic leukemia patients." (PMID 29258207, 2017). "Moreover, tumor-derived galectin-1 was demonstrated to attenuate the expansion of the CD4+CD25+FOXP3+ Treg cells in human Hodgkin lymphomas." (PMID 37047471, 2023). "In Hodgkin lymphoma galectin-1 is a predictive marker for evaluation of prognosis of the patients." (PMID 24589677, 2014). "Galectin-1 (LGALS1) may act as an autocrine negative growth factor that regulates cell proliferation and is involved in Hodgkin lymphoma." (PMID 34563241, 2021).
myeloma (9 papers, 2015 to 2024). "Recent data support a role for the glycan-binding protein galectin-1 in both myeloma cells and in the MM microenvironment." (PMID 30813402, 2019). "Research of multiple myeloma revealed that serum galectin-1 was positively correlated to soluble CD163, indicating that galectin-1 might contribute to the activation of M2-like macrophages." (PMID 37047471, 2023). "However, another study reported that LGALS1 expression in multiple myeloma cells was upregulated under hypoxic conditions and that downregulation significantly reduced the tumor burden in a mouse model." (PMID 34195077, 2021). "Finally, we assessed the impact of myeloma cells on galectin-1 expression during osteoclastogenesis." (PMID 30813402, 2019). "High Galectin-1 levels measured by gene expression profiling correlated with worse outcome in multiple myeloma, and knockdown of Galectin-1 in multiple myeloma cells resulted in smaller tumor formation and less lytic bone damage in an intra-tibeal injection model." (PMID 29580262, 2018). "Hence, further studies are required to determine the prognostic role of LGALS1 in multiple myeloma." (PMID 34195077, 2021). "We also determined the expression of immune suppressive genes, and observed an increase in immune escape score and high expressions of CD47, LGALS1 and TGFB1 in low-immune response myeloma." (PMID 36717896, 2023). "Hypoxia increases Galectin-1 in multiple myeloma but BP-ALL cells in co-culture with OP9 at 22% and 3% O2 contained comparable Galectin-1 protein levels." (PMID 29580262, 2018). "For instance, in myeloma cell lines, but not in B-cell lines, galectin-1 promotes survival via an enhanced signaling of pAKT and pERK1/2—an effect that depends on the expression of a specific isoform of CD45." (PMID 39273216, 2024). "Galectin-1 (LGALS1) release is a common feature of inflammatory cell death, including necroptosis, while KLF6 downregulation has been shown to rescue the death of bortezomib-resistant multiple myeloma cells." (PMID 37397499, 2023).
autoimmune disease (8 papers, 2010 to 2025). A disorder resulting from loss of function or tissue destruction of an organ or multiple organs, arising from humoral or cellular immune responses of the individual to their own tissue constituents. "It was shown that galectin-1-defficient mice had dysfunctional Tregs, exhibited increased production of pro-inflammatory cytokines and are susceptible to development of autoimmune diseases." (PMID 35949491, 2022). "Galectin-1−/− animals have increased susceptibility to autoimmune diseases, such as experimental autoimmune encephalitis, and therapeutic administration of galectin-1 has been effective in models of experimental autoimmune encephalitis, collagen-induced arthritis, and graft versus host disease." (PMID 26216879, 2015). "Since galectin-1 is involved in the modulation of immune responses and shows anti-inflammatory properties in autoimmune diseases, investigations on the role of galectin-1 were prompted in a mouse model of experimental autoimmune epididymo-orchitis (EAEO)." (PMID 39792160, 2025). "Galectin-1 supports immune tolerance, as evidenced in autoimmune disease models, while Gal-3 modulates cytokine output, influencing T helper cell polarization." (PMID 40806347, 2025). "Overall, galectin-1 exerts dual roles in physiological conditions versus certain autoimmune diseases." (PMID 37047471, 2023). "We attempted to prolong their life by injecting galectin-1, which has been reported to suppress other autoimmune diseases, starting at day 7 of birth." (PMID 21124798, 2010). "Bone marrow mesenchymal stem cells constitutively express galectin-1, 3, and 8, leading to the suppression of T-cells and alleviation of inflammatory reactions such as those seen in graft versus host disease (GVHD) and autoimmune disorders." (PMID 39170483, 2024).
colitis (8 papers, 2014 to 2025). Inflammation of the colon. "The enhanced susceptibility of Lgals1−/− mice to developing DSS-induced colitis with respect to WT mice suggests that endogenous galectin-1 modulates intestinal inflammatory responses." (PMID 34262567, 2021). "Mice deficient in the Lgals1 gene displayed an increase susceptibility to developing colitis." (PMID 34262567, 2021). "It was found that the regulation of goblet cells by butyrate is mediated by galectin-1 gene stimulation of the regulatory glycosylation enzyme that is an enzyme found to have protective effects in experimental research into colitis." (PMID 35360686, 2022). "Altogether, these data support the immunomodulatory function of endogenous galectin-1 in DSS-induced colitis." (PMID 34262567, 2021). "In the present study, the acute dextran sulfate sodium (DSS)-induced model of colitis was used to study the function of endogenous galectin-1 during the development of intestinal inflammation." (PMID 34262567, 2021). "In this study, the acute dextran sulfate sodium (DSS)-induced model of colitis was used to study the function of endogenous galectin-1 during the development of intestinal inflammation." (PMID 34262567, 2021). "Several studies have demonstrated that administration of recombinant galectin-1 suppressed experimental colitis by modulating adaptive immune responses altering the fate and phenotype of T cells." (PMID 34262567, 2021). "Adoptive transfer of WT/Tregs was sufficient to modulate the enhanced severity of DSS-induced colitis in observed in Lgals1−/− mice in contrast to what was observed in colitic Lgals1−/− mice treated with KO/Treg cells." (PMID 34262567, 2021). "Studies have also reported that Galectin-1 ameliorates mouse colitis by conferring oligosaccharide-dependent anti-inflammatory properties on macrophages, and the biomaterial containing Galectin-1 inhibits macrophage M1 polarization and promotes M2 polarization, thereby promoting tissue repair." (PMID 36591221, 2022). "Additionally it was reported that galectin-1 was able to confer anti-inflammatory capacities to macrophages via inducing secretion of IL-10, thus ameliorating the murine dextran sodium sulfate-induced colitis." (PMID 37047471, 2023). "However, Lgals1−/− mice exhibited an exacerbated inflammatory response to DSS-induced colitis as shown by the enhanced total body losses and disease activity indexes that ultimately led to significantly reduced survival of colitic Lgals1−/− mice compared to WT mice." (PMID 34262567, 2021). "Thirty-two C57BL/6 mice were randomly assigned to one of the four groups: control, acute colitis, galectin-1, and DSS+galectin-1." (PMID 31999939, 2020). "To further confirm that in the absence of endogenous galectin-1 a functional defect in the Foxp3+CD4+Treg cells is involved in the severe response to DSS-colitis observed in Lgals1−/− mice, we adoptively transferred CD25highCD127low/− Foxp3+CD4+Treg cells (WT/TRegs) into colitic Lgals1−/− mice." (PMID 34262567, 2021). "To further define the key role played by Foxp3+CD4+Treg cells in the exacerbated inflammatory response of Lgals1−/− mice to DSS-induced colitis, we assessed whether adoptive transfer of WT Foxp3+CD4+Treg cells could reverse the enhanced inflammatory response observed in colitic Lgals1−/− mice." (PMID 34262567, 2021). "However, this does not rule out a role in colitis, as galectin-1 can bind both epithelial cells and lymphocyte glycans, resulting in apoptosis and other cell regulations." (PMID 26885508, 2016).